VIM (vimentin)
Diseases named in the same sentence as VIM in open-access papers (continued):
Sharing a sentence is not in itself a finding about the gene and the disease.
Benign breast tumors (1 paper, 2015). "Benign breast tumors (group IV) had the highest E-cadherin expression, and the lowest N-cadherin and vimentin expression." (PMID 26702618, 2015).
bile duct adenoma (1 paper, 2014). A benign, well-demarcated polypoid neoplasm arising from the bile duct epithelium. "By immunohistochemistry, clear cell bile duct adenomas are positive for CK7, CEA, and EMA and are negative for CK20, HepPar-1, chromogranin A, prostate specific antigen (PSA), and vimentin." (PMID 24955270, 2014).
bile duct cancer (1 paper, 2022). "Studies have found that LNC-LFAR1 expression inhibition can inhibit bile duct cancer cell proliferation, migration, and invasion, and reduce the expression of Vimentin, Tgf-β1, Smad2, and Smad4." (PMID 35456382, 2022).
bladder leiomyoma (1 paper, 2024). A well-circumscribed benign smooth muscle neoplasm arising from the bladder. "Immunohistochemically, the majority of bladder leiomyomas show significant and wide immunoreactivity for smooth muscle actin, muscle-specific actin, desmin, and vimentin, whereas typically absent reactivity of antibodies for cytokeratin and S100 protein." (PMID 38983791, 2024).
blastoma (1 paper, 2013). A malignant neoplasm composed of undifferentiated cells. "On immunohistochemistry expression of cytokeratin and vimentin is seen in the blastomatous component, the epithelial elements in blastomas react positively for keratin, carcinoembryonic antigen, epithelial membrane antigen, and milk fat globulin." (PMID 23758909, 2013).
Bowen’s disease (1 paper, 2022). "Bowen’s disease acquiring de novo invasive capacity shows more advanced EMT markers at the invasive front such as increased Vimentin." (PMID 35666359, 2022).
bullous keratopathy (1 paper, 2023). "The corneal endothelial cells were positive for immunohistochemical stains, specifically vimentin and fibronectin, in all scarred corneas, such as in post-traumatic scarring and bullous keratopathy." (PMID 37323319, 2023).
calcification (1 paper, 2024). Process by which organic tissue becomes hardened by the physiologic deposit of calcium salts. "We showed that fibrosis, pathological gingival calcifications and increased expression of various profibrotic and pro-osteogenic proteins such as POSTN, SPARC and VIM were common findings." (PMID 38664418, 2024).
carcinoid tumor (1 paper, 2014). A slow growing neuroendocrine tumor, composed of uniform, round, or polygonal cells having monotonous, centrally located nuclei and small nucleoli, infrequent mitoses, and no necrosis. "Thus, PT lacks cytokeratins which are found in most carcinomas, carcinoid tumors and epithelial organs, but expresses vimentin which is found in tumors of mesenchymal origin, not carcinomas." (PMID 24670249, 2014).
central nervous system infection (1 paper, 2022). "Some previous studies validated that vimentin-mediated NF-κB signaling plays an important role in central nervous system infection." (PMID 35807435, 2022).
cerebellar ataxia (1 paper, 2025). A neurological syndrome characterized by clumsy and uncoordinated movement of the limbs, trunk, and cranial muscles. "Recently, anti-vimentin antibodies have been reported to be associated with cerebellar ataxia and pyramidal tract damage." (PMID 41438737, 2025).
cervical squamous intraepithelial lesion (1 paper, 2025). "We found that PGRMC1 binds to and regulates VIM phosphorylation to promote cervical squamous intraepithelial lesion progression." (PMID 41153737, 2025).
Chlamydia infection (1 paper, 2018). "We concluded that both OGT activity and vimentin glycosylation sites are required for IF reorganization during Chlamydia infection, and are co-opted by this pathogen to promote inclusion integrity and growth." (PMID 29513221, 2018). "We found that 5SGlcNAc treatment inhibited the formation of a vimentin meshwork around the inclusion, consistent with a requirement for vimentin glycosylation in IF remodeling during Chlamydia infection." (PMID 29513221, 2018). "Our data suggest a model wherein glycosylation of the N-terminal vimentin head domain (red), particularly on S49, promotes homotypic vimentin-vimentin interactions, and assembly and/or maintenance of mature IFs under both homeostatic and Chlamydia infection conditions." (PMID 29513221, 2018).
chlamydial infections (1 paper, 2016). "Vimentin has also been implicated as a component of epithelial tight junctions and may be a cellular target for CPAF proteolysis late in chlamydial infections." (PMID 26829550, 2016).
cholesteatoma (1 paper, 2023). A pathologic process characterized by the proliferation of keratinizing squamous epithelium resulting in the accumulation of keratin and cells in the middle ear and/or mastoid. "Cholesteatoma sections exhibited colocalization of INHBA and vimentin, a marker for fibroblasts, indicating that INHBA was present at the protein level in the cholesteatoma fibroblasts." (PMID 37537159, 2023).
chondroma (1 paper, 2022). A benign well circumscribed neoplasm of hyaline cartilage arising from bone or soft tissue. "On histopathological examination, the tumor was diagnosed as chondroma; Vimentin, Ki-67 (6%), SOX-9, and S-100 stained positive, but CK, CK18, EMA, CD34 and GFAP stained negative." (PMID 35692788, 2022). "On histopathological examination, the tumor was diagnosed as chondroma; Vimentin, S-100 and Ki-67(2%) stained positive, but EMA, CK, CK18, CD34, SOX-9 and GFAP stained negative by ICH." (PMID 35692788, 2022). "The pathological diagnosis was chondroma; ICH showed Vimentin and S-100 stain was positive, but Ki-67, CK, CK18, EMA, CD34 and GFAP stain was negative." (PMID 35692788, 2022).
chronic kidney disease (1 paper, 2025). Impairment of the renal function secondary to chronic kidney damage persisting for three or more months. "Loss of HNF4A expression and gain of vimentin expression were reciprocal and gradual during both acute and chronic kidney disease, as indicated by immunohistochemistry." (PMID 39954965, 2025). "Thus, the reduction of HNF4A and increase of vimentin expression were connected to both acute and chronic kidney disease and represented a stereotypic injury response of the PT, resulting in dedifferentiation." (PMID 39954965, 2025).
chronic lung disease (1 paper, 2022). According to the definitions of the American and British Thoracic Societies, including pulmonary functional tests, X-rays, and CT scans for items such as fibrosis, bronchiectasis, bullae, emphysema, nodular or lymphomatous abnormalities. "Owing to its importance as a mesenchymal marker, the expression of vimentin is extensively demonstrated during lung remodeling as one of the driver for the pathogenesis of chronic lung diseases." (PMID 35573702, 2022). "Different PTMs on Vimentin intermediate filaments have been explored for their regulatory role in development of chronic lung diseases." (PMID 35573702, 2022).
cognitive decline (1 paper, 2024). "Seven of the 22 peptides associated with the frail vs control diagnostic contrast and cognitive decline were cytoskeleton-related, including proteoforms of MAP2, VIM, TUBB, DBN1, TUBA8, PALM and NEFM." (PMID 38531951, 2024).
Cognitive impairment (1 paper, 2012). Abnormal cognition is characterized by deficits in thinking, reasoning, or remembering. "The levels of GFAP and vimentin in CSF did not correlate with the severity of the cognitive impairment in PDD or DLB." (PMID 22577599, 2012).
congenital hydrocephalus (1 paper, 2024). Hydrocephalus that is present at birth. "The consistency of our findings with previous literature, which links ependymal injury and congenital hydrocephalus to Vimentin upregulation, indicates a common pathway that might be crucial for understanding iNPH development." (PMID 39118132, 2024).
cortical cataract (1 paper, 2025). A cataract (disease) that involves the lens cortex. "Vimentin undergoes degradation with calcium overload, which is among the causes of cortical cataracts." (PMID 40649110, 2025).
cortical dysplasia (1 paper, 2010). "In our ferret model of cortical dysplasia, early signs of radial glial differentiation are loss of pial attachment and parallel alignment as occurs in the vimentin-positive cells." (PMID 21060844, 2010). "In our ferret model of cortical dysplasia, the expression of BLBP in radial glia is decreased after MAM treatment; however the remaining BLBP+ radial glial cells are relatively spared from disruption compared with the severely disorganized vimentin+ cells." (PMID 21060844, 2010).
craniopharyngioma (1 paper, 2025). A benign, partly cystic, epithelial tumor of the sellar region, presumably derived from Rathke pouch epithelium. "A previous study has demonstrated that EMT occurred in craniopharyngioma, proofed by the expression of Vimentin and E-cadherin in tumor sections, and associated with tumor recurrence." (PMID 40299526, 2025).
cryptorchidism (1 paper, 2025). The failure of one or both testes of a male fetus to descend from the abdomen into the scrotum during the late part of pregnancy. "Changes in vimentin expression patterns in Sertoli cells have been found in various pathological situations, including cryptorchidism." (PMID 40564248, 2025). "The authors proposed that Sertoli cells are affected in cryptorchidism, and altered vimentin filament distribution correlates with increased germ cell apoptosis." (PMID 40564248, 2025).
cutis laxa (1 paper, 2012). Cutis laxa (CL) is an inherited or acquired connective tissue disorder characterized by wrinkled, redundant and sagging inelastic skin associated with skeletal and developmental anomalies and, in some cases, with severe systemic involvement. "The influence of DS decorin on vimentin offers a novel explanation for the reported delay in wound healing of Dcn−/− mice and for the cutis laxa of EDS patients with defects in the biosynthesis of decorin." (PMID 23226541, 2012).
cystinosis (1 paper, 2022). Cystinosis is a metabolic disease characterized by an accumulation of cystine inside the lysosomes, causing damage in different organs and tissues, particularly in the kidneys and eyes. "To test our hypothesis that a significant loss of kidney epithelial cells in cystinosis patients could be compensated with an attempt for regeneration, we first explored whether undifferentiated cells, characterized by expression of vimentin, are present in the urine of cystinosis patients." (PMID 35406807, 2022).
deafness (1 paper, 2023). An inherited or acquired condition characterized by the complete loss of the ability to hear from one or both ears. "The current work found a series of DEGs related to sensory epithelial development and cytoskeleton organization through functional enrichment and PPI network analysis, including ATOH1, VIM, PRPH and NEFL, which may be involved in the pathogenesis of ELMOD3 causing deafness." (PMID 37708136, 2023).
dendritic cell sarcoma (1 paper, 2020). A sarcoma that involves the dendritic cell. "U-DCS is growing with typical dendritic cell morphology in tissue and expresses the dendritic cell sarcoma immunophenotypic markers S100 protein, MHCI, MHCII, and vimentin." (PMID 33277516, 2020).
dermal neoplasm (1 paper, 2024). "The histopathological examination revealed a rather well-circumscribed dermal neoplasm extending into subcutaneous tissue with high mitotic activity and immunohistochemical positivity for vimentin, CD99, and Bcl-2, but not for markers like CD45, HMB45, and S-100." (PMID 39022482, 2024).
dermatofibroma (1 paper, 2025). "DFSP stains positive for CD34 and vimentin and negative for S100, factor XIIIa, podoplanin D2-40, stromelysin III, and cathepsin K. This helps differentiate DFSP from benign entities such as dermatofibroma." (PMID 41393578, 2025).
desmoplastic fibroma (1 paper, 2024). A extremely rare bone tumor characterized by abundant collagen formation and a fibrous stroma, without evidence of mitosis or pleomorphism. "Desmoplastic fibromas of the bone typically show diffuse and strong immunohistochemical expression of vimentin and focal positivity for SMA, similar to desmoplastic fibroblastoma." (PMID 39830562, 2024).
diffuse astrocytoma (1 paper, 2020). A low-grade (WHO grade II) astrocytic neoplasm.
duodenal tumour (1 paper, 2022). "Additionally, activated c‐JUN promotes the epithelial–mesenchymal transformation of duodenal tumour cells by upregulating the expression of VIM to enhance their invasion and migration abilities, resulting in tumour progression." (PMID 36178086, 2022).
echovirus infection (1 paper, 2020). "Changes in the vimentin network brought about with different media and treatments correlated with successful baculovirus transduction and echovirus infection, suggesting that the vimentin network has a previously unknown role in infection." (PMID 31619557, 2020).
embryonal carcinoma (1 paper, 2025). A non-seminomatous malignant germ cell tumor characterized by the presence of large germ cells with abundant cytoplasm resembling epithelial cells, geographic necrosis, high mitotic activity, and pseudoglandular and pseudopapillary structures formation. "Silencing of OCT4 and VIM genes resulted in decreased proliferation, migration, invasion, chemoresistance and tumor progression in embryonal carcinoma cells and embryonic stem cells." (PMID 40535773, 2025).
emphysema (1 paper, 2024). "Future investigations should be aimed at assessing the differential expression of p63 and vimentin in patients with normal lung function (as measured by FEV1 and FEV1/FVC) and imaging patterns of emphysema, potentially indicating a specific COPD phenotype." (PMID 38276115, 2024).
Endometrioid ovarian carcinoma (1 paper, 2024). "Endometrioid ovarian carcinoma typically exhibits positive immunoreactivity for ER and PR, as well as for CA125 and vimentin, markers that are generally negative in primary MOC." (PMID 39040449, 2024).
enterovirus infection (1 paper, 2020). "Our findings show that human enterovirus infection leads to massive vimentin rearrangements that harbor the replication site, as was indicated by the higher association of dsRNA, 2A, and 3D polymerase with the vimentin cages." (PMID 31619557, 2020). "In conclusion, we show that viral protein synthesis during enterovirus infection induces formation of a vimentin-enwrapped perinuclear compartment harboring replicating dsRNA and nonstructural proteins 3D and 2A." (PMID 31619557, 2020).
epidermal cysts (1 paper, 2023). "Interestingly, when adult mouse cells are used to do organoid cultured 1, dermal cells are not attached to the epidermal cyst, as demonstrated by immunostaining for Vimentin and K14." (PMID 37284452, 2023).
epithelioid hemangioma (1 paper, 2020). A hemangioma characterized by the presence of epithelioid endothelial cells. "VIM, located on chromosome 10p13, encodes vimentin and has been described in fusions with FOS in a subset of epithelioid hemangioma." (PMID 32461620, 2020).
fallopian tube carcinoma (1 paper, 2016). A carcinoma that arises from epithelial cells of the fallopian tube. "The NAFs from the normal human fallopian tube fimbriae and the CAFs from the fallopian tube carcinoma were universally positive for vimentin." (PMID 27379403, 2016).
fibroma (1 paper, 2009). A non-metastasizing neoplasm arising from the fibrous tissue. "Myofibromas/myofibromatosis and fibromas may be highly collagenic, and express vimentin, HHF35 and muscle-specific actin; they are CD34 negative." (PMID 19893953, 2009).
Flavivirus Infections (1 paper, 2026). Infections with viruses of the genus FLAVIVIRUS, family FLAVIVIRIDAE. "Our previous work indicated that MEK1/2 inhibitors can induce the dispersion of vimentin, but their potential impact on flavivirus infection remains unclear." (PMID 41137718, 2026).
follicular dendritic cell sarcoma (1 paper, 2015). A neoplasm composed of spindle to ovoid cells which have morphologic and immunophenotypic characteristics of follicular dendritic cells. "Follicular dendritic cell sarcoma (FDCS) is specifically immunopositive to CD21, CD35, and/or CD23, vimentin, fascin, HLA-DR, EMA, D2-40, clusterin, and CXCL13." (PMID 25889780, 2015).
follicular lymphoma (1 paper, 2024). Follicular lymphoma is a form of non-Hodgkin lymphoma characterized by a proliferation of B cells whose nodular structure of follicular architecture is preserved. "High intratumoral expression of vimentin was shown to be a predictive marker of histological transformation in follicular lymphoma patients." (PMID 39123440, 2024).
gastric intestinal type adenocarcinoma (1 paper, 2020). An adenocarcinoma of the stomach arising on a background of intestinal metaplasia. "Next, Oncomine database analysis indicated that increased VIM expression was significantly associated with diffuse GC compared with gastric intestinal type adenocarcinoma based on results from three clinical cohorts (P = 0.002)." (PMID 31981446, 2020).
gastric ulcer (1 paper, 2024). An ulcerated lesion in the mucosal surface of the stomach. "Thus, further experiments are needed to fully differentiate whether the reduction in inflammation indicated by vimentin was solely due to the healing of gastric ulcers, or also partially due to the anti-inflammatory effects of omeprazole." (PMID 39518828, 2024).
gastroesophageal reflux disease (1 paper, 2024). A chronic disorder characterized by reflux of the gastric and/or duodenal contents into the distal esophagus. "In samples with histologic evidence of gastroesophageal reflux disease, there is an increase in these α-SMA+ and vimentin+ myofibroblasts compared to normal biopsies, although the percentage of myofibroblasts compared to fibroblasts, remained quite small." (PMID 39056656, 2024).
giant cell arteritis (1 paper, 2023). "Indeed, immunohistochemistry of temporal artery biopsies of giant cell arteritis (GCA) patients showed bright IST1 labeling of CD68+ macrophages and vimentin+ fibroblasts." (PMID 37200023, 2023).
glomerulonephritis (1 paper, 2020). A renal disorder characterized by damage in the glomeruli. "Otherwise, the overexpression of VIM in renal tubules and interstitial tissue of the CP group was noted may be attributed to glomerulonephritis or tubule-interstitial injury, respectively." (PMID 33117167, 2020).
gout (1 paper, 2024). A condition characterized by painful swelling of the joints, which is caused by deposition of urate crystals. "Immunostaining of ankle joint from gout model mice showed that a majority (56.6%) of CXCL5+ cells co-stained with fibroblast cell marker vimentin and to a lesser extent, co-stained with markers for macrophage (Iba-1) and mast cell (avidin) (30.0% and 12.3%, respectively)." (PMID 38627393, 2024).
hantavirus infection (1 paper, 2022). "Early in African swine fever virus (ASF) and hantavirus infection, vimentin showed stellate aggregation on one side of the Vero cells and then rearranged into a cage structure around the virus replicator." (PMID 34983604, 2022).
HCMV infection (1 paper, 2011). "During the initial phase of HCMV infection, the virus requires an intact network of vimentin intermediate filaments, which appear to facilitate capsid trafficking and/or docking to the nuclear envelope." (PMID 21407806, 2011).
hemochromatosis (1 paper, 2018). A disorder of iron metabolism characterized by a triad of HEMOSIDEROSIS; LIVER CIRRHOSIS; and DIABETES MELLITUS. "Examples are mitogen-activated protein kinase (MAPK)/RAS family members (HRAS and NRAS), hemochromatosis (HFE), BRD7, ATM, vimentin (VIM), which are upregulated in poorly differentiated cell lines and in human HCC datasets." (PMID 30176945, 2018).